INS (insulin)
Diseases named in the same sentence as INS in open-access papers (continued):
Sharing a sentence is not in itself a finding about the gene and the disease.
Insulin resistance (continued). "Participants with lower serum hydrogen bicarbonate concentration showed both significantly increased insulin resistance and a significantly elevated serum insulin concentration." (PMID 28829398, 2017). "Insulin resistance (IR) is defined as the inability of insulin to increase cellularglucose uptake and utilization, leading to compensatory hyperinsulinemia." (PMID 28811358, 2017). "The body weight, BMI, systolic and diastolic blood pressure, HbA1c, fasting plasma glucose, insulin, homeostasis model assessment-insulin resistance (HOMA-IR), triglycerides, SMI, and body fat were significantly reduced by luseogliflozin at 12 weeks." (PMID 28253918, 2017). "Impairment of insulin signaling is central to the development of insulin resistance, leading to the development of type 2 diabetes and liver disease." (PMID 28736524, 2017). "In contrast, dynamic tests exhibited insulin resistance in IH animals as shown by the trend to a lower blood glucose decrease after insulin challenge (i.e. smaller blood glucose AUC and nadir)." (PMID 28894286, 2017). "Although AMPK activation and increasing insulin sensitivity seem to be effective therapeutic approaches for insulin resistance, AMPK activation is the representative catabolic pathway and insulin is the representative anabolic hormone." (PMID 29259227, 2017). "In the presence of insulin resistance, the use of glucose in peripheral tissues has been obstructed, and insulin cannot effectively suppress lipolysis, so that superfluous free fatty acids are released." (PMID 29057036, 2017). "Insulin resistance mainly shows that the insulin action in liver and skeletal muscle is lower than that in healthy subjects." (PMID 29089472, 2017). "HFD usually results in obesity leading to insulin resistance, whereas low dose of STZ causes moderate destruction of insulin secretion." (PMID 28693595, 2017). "PCOS therapies that target at improving insulin resistance are quite well established and are reported to reduce both insulin-enhanced ovarian androgen synthesis and the insulin-mediated inhibition of SHBG31,32." (PMID 29074860, 2017). "Type 2 diabetes is characterized by impaired insulin secretion and insulin resistance in peripheral tissues." (PMID 28928791, 2017). "The sirtuin family of proteins is downregulated in cells with high insulin resistance, resulting in an increase in insulin sensitivity." (PMID 28531120, 2017). "In acromegaly, a condition of GH excess, there is low body fat with insulin resistance, and in Laron’s syndrome, due to an inactivating mutation in the growth hormone receptor (GHR), there is high body fat with insulin sensitivity." (PMID 28713554, 2017). "Specifically, short-term treatment with IL-6, improved glucose control and insulin sensitivity, whereas long-term treatment with IL-6 contributed to glucose intolerance and insulin resistance." (PMID 28706484, 2017). "Effects of insulin and glucose on fertility are of great interest due to the rise of insulin resistance and type-2 diabetes prevalence among women of reproductive age." (PMID 28974690, 2017). "In the current study, we investigated the progressive changes in insulin secretory response and the development of tissue-specific insulin resistance in the HFHF diet-fed adult Taiwan Lee-Sung miniature pigs." (PMID 29046729, 2017). "Our data indicate for the first that maternal butyrate diet can induce whole-body insulin resistance and inhibits insulin signaling pathway and glucose uptake in skeletal muscle in adult offspring." (PMID 28055958, 2017). "This resulted in increased translocation and expression of GLUT-4, which further resulted in BM-MSC–mediated amelioration of insulin resistance in peripheral insulin target tissues." (PMID 28515792, 2017). "Type 2 diabetes mellitus (T2DM) is a complex, chronic metabolic disease with hyperglycemia arising from insulin resistance, progressive pancreatic beta-cell failure and insufficient insulin secretion." (PMID 28930273, 2017).
Insulin resistance (continued). "Investigations were carried out for fasting blood glucose, fasting serum insulin, insulin resistance (IR), the lipid profile, lipoprotein band lipoprotein phospholipase A2, and non-high-density lipoprotein cholesterol (non-HDL-C)." (PMID 29099041, 2017). "In fact, it can be stated that insulin sensitivity falls and insulin resistance is dominant for hyperinsulinemia in PCOS women." (PMID 29387827, 2017). "IL-6 leads to increased insulin resistance by blocking the IRS-mediated insulin signaling in hepatocytes and muscle cells causing impaired insulin-stimulated glucose uptake into muscle cells." (PMID 28555043, 2017). "Insulin resistance and hyperinsulinemia are believed to be key contributing factors to the pathogenesis of PCOS; excessive amounts of insulin are directly associated with the increased ovarian production of androgens and metabolic features of PCOS." (PMID 32153805, 2017). "In obesity and intestinal insulin resistance, there is an impairment in the insulin-stimulated GLUT2 internalization in the enterocyte; which has been suggested to restrain the normal GU in the intestine." (PMID 28183816, 2017). "In these children, hyperinsulinemia compensates for insulin resistance and maintains the homeostasis of insulin." (PMID 28193268, 2017). "In conclusion, this study suggests that, MHY2013 is a novel PPAR pan agonist that improves obesity-induced insulin resistance, dyslipidemia and hepatic steatosis and elevates insulin-sensitizing hormones in the blood." (PMID 28129657, 2017). "Our findings imply that hyperglycemia stimulates endogenous c-peptide (and therefore insulin) secretion even in critically ill patients with acute-on-chronic insulin resistance." (PMID 28497374, 2017). "In the case of insulin resistance, insulin secretion from β-cells can increase 4-fold while β-cell mass can increase 2-fold." (PMID 29209160, 2017). "Insulin resistance is generally regarded as a pathological condition in which cells fail to respond to the normal actions of insulin, leading to high blood glucose." (PMID 28935866, 2017). "HIG compared to SIG presented smaller insulin (p = 0.02), triglyceride levels (p = 0.01), and insulin resistance by the HOMA-IR (p = 0.01), along with TYG index (p = 0.02)." (PMID 29412381, 2017). "In CAV3 knockout mice, the IR protein in skeletal muscle decreased rapidly after 15 min of insulin stimulation, which led to the occurrence of insulin resistance, decreased glucose uptake and decreased glycogen synthesis." (PMID 29206848, 2017). "We find that this increase in cell death in FAK-deficient mice occurs before the development of significant changes in body composition or insulin sensitivity, identifying it as an early factor in the pathogenesis of insulin resistance." (PMID 28165007, 2017). "In order to prevent the development of insulin resistance, it is of importance to understand the patho-physiological mechanisms of insulin resistance and to identify early biomarkers of decreased insulin sensitivity." (PMID 28617863, 2017). "Altogether, these results strongly implicate dietary Se deprivation in both insulin resistance and defective insulin production under pathophysiological conditions reminiscent of late stage type‐2 diabetes as the G3 Terc−/− mice age." (PMID 27653523, 2017). "Rosiglitazone, a PPARγ agonist, has been reported to enhance the insulin sensitivity of cells and tissues, alleviate insulin resistance, and exert a protective effect on nerve cells." (PMID 28790390, 2017). "The vitamin D has important biological functions, such as modulating immunity system, influencing insulin secretion and improving insulin resistance, which are involved in the etiology of DN and more likely to be influenced by VDR gene polymorphisms." (PMID 28851298, 2017).
Insulin resistance (continued). "In some studies, insulin resistance was the primary abnormity of IGT, while IFG was more associated with insulin secretion." (PMID 28199386, 2017). "The Homeostasis Model Assessment (HOMA-IR) was used to determine the presence of insulin resistance based on cut-off values of ≤2.71 for normal insulin levels and >2.71 for insulin resistance, as established for the adult Brazilian population." (PMID 28492722, 2017). "Unfortunately, serum insulin concentrations were too low to be detected faithfully in the present study, thus hampering calculating indicators for insulin resistance, such as the HOMA-IR index." (PMID 29053583, 2017). "SOCS3 links the IL-6–STAT3 pathway to insulin signaling and plays a critical role in the development of insulin resistance in type 2 diabetes." (PMID 28706484, 2017). "This can potentially lead to a reduction and abnormal function of mitochondria and ultimately result in cellular abnormalities (lipid accumulation, reduced fat oxidation, and insulin signaling) related to insulin resistance." (PMID 28883895, 2017). "PCOS patients were heavier, with significantly higher insulin, insulin resistance and testosterone values." (PMID 28723965, 2017). "Even in the presence of insulin resistance, near-normal glucose tolerance in a patient can be achieved so long as there is sufficient insulin secretion to meet the elevated requirements necessitated by insulin resistance." (PMID 29214024, 2017). "Body weight, fasted blood glucose level, fasted insulin level, homeostasis assessment of insulin resistance (HOMA-IR) index and lipid profile were detected." (PMID 28107465, 2017). "In parallel, FTI-277 prevented burn-induced insulin resistance (i.e., impaired insulin signaling, suppressed insulin-stimulated glucose uptake), increases in lactate production and proteolysis in skeletal muscle, and hyperlactatemia in mice." (PMID 28747716, 2017). "The classical theory of insulin resistance states that obesity leads to insulin resistance, insulin resistance tends to increase plasma glucose which stimulates increased insulin secretion." (PMID 28767672, 2017). "Impairment of insulin clearance is being increasingly recognized as a critical step in the development of insulin resistance and metabolic disease." (PMID 28396653, 2017). "There is strong evidence that a persistent inflammatory state, as occurs in hemodialysis patients, interferes with normal insulin signaling and inflammatory markers as interleukin 6 and C-reactive protein correlated with insulin resistance in clinical trials." (PMID 28719612, 2017). "BBR administration significantly decreased serine phosphorylation and increased tyrosine phosphorylation of IRS in HepG2 cells, which improved insulin signaling and thus in turn ameliorated insulin resistance." (PMID 29164155, 2017). "Although the exact mechanism causing this significant correlation was not determined, we suggest that because saturated fat is a known antagonist of insulin and contributor to insulin resistance which then leads to higher insulinemia." (PMID 28697750, 2017). "The release of insulin is biphasic and evidence have put forward that impaired insulin secretion precedes insulin resistance and that first‐phase insulin secretion is lost already when the patient has impaired glucose tolerance (IGT) or prediabetes." (PMID 29122960, 2017). "Our results indicated that CLW prevented rampant insulin secretion which exhausts β-cell function and exacerbates insulin resistance." (PMID 29104217, 2017). "The identification of stem cells that possess the potential to differentiate into insulin-producing cells (IPCs), improve pancreatic regeneration, and ameliorate insulin resistance offers an alternative to islet cell transplant." (PMID 28515792, 2017).
Insulin resistance (continued). "Under the condition of insulin resistance, cells in insulin dependent tissues, principally adipose tissues and muscles, are resistant to insulin and fail to respond to it effectively, inducing a high level of serum glucose." (PMID 28212343, 2017). "According to past reports, there were some reports about the relationship between AGEs and insulin secretion and insulin resistance in the human healthy subjects; however, there were few reports about type 2 DM subjects." (PMID 28695132, 2017). "An increased level of free fatty acids can suppress insulin-stimulated glucose uptake, thus contributing to the development of insulin resistance." (PMID 29340108, 2017). "Hyperglycemia during type 2 diabetes is initially mediated by insulin resistance, but later inadequate production of insulin contributes significantly to progression of disease." (PMID 28765602, 2017). "In this study, we also measured insulin-resistance phenotype levels, e. g., fasting blood glucose levels, fasting insulin levels, HOMA-IR, and GTT." (PMID 28570676, 2017). "The homeostatic model assessment for insulin resistance (HOMA-IR) is an indirect calculation of insulin resistance (IR) using insulin and glucose levels." (PMID 28930273, 2017). "Only about 100 transcribed genes responded differently to hyperinsulinemia in women with systemic insulin resistance compared to insulin sensitive women." (PMID 28570579, 2017). "We assessed HOMA insulin resistance, a measure of hepatic insulin sensitivity, in two RCTS of a two-day IER versus CER amongst subjects who are overweight or obese." (PMID 28106818, 2017). "The insulin resistance index calculated by the HOMA model (HOMA-IR) using fasting serum levels of insulin (μIU/ml) and glucose levels (mmol/l) indicated that males and females of DF1-HCD group were insulin resistant compared to CF1-CD group." (PMID 28078101, 2017). "Other plant saponins such as ginsenosides in ginseng have been reported to have anti-diabetic effects by potentiating glucose-stimulated insulin secretion and reducing insulin resistance." (PMID 29104217, 2017). "Lycopene showed to improve cognitive functions in rat models of insulin resistance, in parallel with improvement of insulin signaling deficits, oxidative stress and neuroinflammation." (PMID 29141041, 2017). "We measured the fasting blood glucose, insulin, hemoglobinbA1c, homeostasis model assessment for insulin resistance (HOMA-IR), carboxymethyl lysine, total antioxidant capacity, and malondialdehyde levels at the beginning and the end of the study." (PMID 28885566, 2017). "For serum insulin concentration, we observed that HFSTZ-induced hyperinsulinemia (increased insulin level) and insulin resistance (elevated HOMA-IR) were mitigated by APS." (PMID 29258283, 2017). "Regarding its pharmacodynamic effect, it was found to effectively reduce insulin secretion and insulin resistance during pregnancy in both randomized and longitudinal studies." (PMID 29082364, 2017). "Growth hormone elevation induces insulin resistance, hence a subsequent elevation of insulin and the potential for activation of insulin receptor." (PMID 29152592, 2017). "The importance of insulin resistance and beta cell failure to produce insulin in the development of IFBG and type 2 diabetes seems to differ among sub-Saharan African populations compared with European populations." (PMID 28144712, 2017). "Impaired insulin delivery and signaling in ECs have also been observed in human patients with type 2 diabetes and obesity with insulin resistance." (PMID 28447033, 2017).
Insulin resistance (continued). "DM is a class of metabolic disorders characterized by hyperglycaemia resulting from the relatively reduced insulin secretion and occurrence of insulin resistance, which can be either due to inherited or environmental factors." (PMID 29050364, 2017). "Previous analyses of the RISC cohort using 1017 baseline samples showed adiponectin levels were positively associated with insulin sensitivity and HDL-cholesterol, partly explaining how low plasma concentrations of adiponectin predict insulin resistance." (PMID 28846711, 2017). "Sirolimus can also enhance β-cell apoptosis and insulin resistance by reducing islet mass, insulin content and insulin sensitivity." (PMID 29280746, 2017). "Our findings show that this polymorphism is also associated with insulin resistance independently of obesity in girls, suggesting that it might have a potential effect or flag a functional polymorphism that has an effect on the action of leptin on insulin metabolism." (PMID 28771179, 2017). "Insulin resistance in adipose tissue is presented as impaired insulin-stimulated glucose transport and blunted inhibition of lipolysis." (PMID 28848738, 2017). "The STAT5A-mediated induction of pyruvate dehydrogenase kinase 4 expression by prolactin results in an inhibition of insulin-stimulated glucose transport in fat cells and contributes to insulin resistance." (PMID 29088862, 2017). "Dietary intake of unsaturated fat increases plasma insulin levels resulting in insulin resistance, and subsequent inflammatory cascade induced by FFA oxidation and hepatic lipotoxicity play a role in progression from NAFLD to cirrhosis and HCC." (PMID 28081181, 2017). "The obese mice had higher fasting glucose and insulin levels, glucose intolerance, and insulin resistance by insulin tolerance test." (PMID 29107299, 2017). "The absence of glucose differences between groups combined with the higher insulin levels in OO as compared NW suggests that the OO group was able to successfully compensate for a higher degree of insulin resistance by increasing insulin secretion." (PMID 29099048, 2017). "In db/db mice, DNJ treatment improved insulin resistance via the activation of the insulin signaling PI3K/AKT pathway in skeletal muscle and the activation of the PKB/GSK-3β signaling pathway in the liver." (PMID 29164155, 2017). "Significantly increased serum leptin and insulin concentrations and impaired insulin tolerance in the male offspring of dams treated with 2.0 mg/kg body weight of Cd and Hg suggested insulin resistance." (PMID 27814245, 2017). "In our in vitro studies, we conclusively demonstrated that AKR1C3 expression is regulated by insulin, mechanistically linking AE and insulin resistance, the two major metabolic features in PCOS." (PMID 28645211, 2017). "DM is characterised by absolute or relative deficiency in insulin secretion by pancreatic β-cells, increased insulin resistance and/or impairment of insulin action in target tissues." (PMID 28933564, 2017). "While in the initial stage of prediabetes, the insulin secretory capacity was increased to compensate for the developing insulin resistance." (PMID 29046729, 2017). "Upon insulin resistance, pancreatic cells enhance their insulin secretion (hyperinsulinemia) to compensate for hyperglycemia on the early onset of T2D." (PMID 28612706, 2017). "Insulin resistance and impaired insulin secretion are the two main components in the pathophysiology of type 2 diabetes mellitus (T2DM); the contributions of these factors are thought to differ between Chinese and Caucasians." (PMID 29069856, 2017). "It is also possible that oestrogen has a protective effect in younger women by increasing insulin sensitivity and reducing insulin resistance, although insulin sensitivity declines after menopause." (PMID 28280865, 2017). "Four gene–diet interactions on fasting insulin levels and homeostatic model assessment of insulin resistance (HOMA-IR) index values were found." (PMID 29113108, 2017).